EIF5A (eukaryotic translation initiation factor 5A)
Diseases named in the same sentence as EIF5A in open-access papers (continued):
Sharing a sentence is not in itself a finding about the gene and the disease.
tumor (continued). "Several studies demonstrate that CPX exerts its anti-tumor effects by inhibiting the activity of deoxyhypusine hydroxylase (DOHH), one of the key enzymes responsible for eIF5A hypusination." (PMID 41256582, 2025). "SPD promotes tumor cell proliferation at low doses via DHPS and eIF5A hypusination, while high doses are cytotoxic due to BSAO-mediated oxidation." (PMID 41408852, 2025). "A few studies have reported that hypusinated eIF5A promotes translation of RhoA and MYC in tumor cells." (PMID 38654332, 2024). "Based on this, the combined blocking of ODC and eukaryotic translation initiation factor 5A (eIF5A) can effectively inhibit c-MYC and produce a synergistic anti-tumor effect in CRC." (PMID 38650895, 2024). "SIRT2, conversely, disrupts cancer cell proliferation by inhibiting eIF5A, while SIRT3 exerts tumor-suppressive effects by regulating mitochondrial ROS and glycolysis." (PMID 39682281, 2024). "Detailed studies have shown that depletion of eIF5A in PDAC cells impairs cell growth ex vivo and orthotopic tumor growth in vivo, while increased expression of eIF5A promotes cell proliferation and tumor formation." (PMID 39125743, 2024). "In order to explore the effect of eIF5A on CCA cells in vivo, a xenografted tumor model was constructed by subcutaneous injection of CCA cells in the back of nude mice." (PMID 35874632, 2022). "As shown in the volcano plot, SU decreased GZMB expression and upregulated genes related to inflammatory activation (FOS, JUN, NFKBIA, DUSP2, JAK1, PIM1), tumor immunity (CD47, PCBP2, EIF5A, PDIA3, EGR1), and DNA damage (H2AFX, DDIT3, GADD45B)." (PMID 34824394, 2021). "Especially notably, in tissues from 205 HCC patients, eIF5A hypusination in tumor stromal lesions was greater than that in adjacent nontumor stromal tissue." (PMID 38689086, 2024). "A greater percentage of patients with low levels of eIF5A hypusination in tumor stromal lesions had TNM stage I and II tumors, whereas a greater percentage of patients with high levels of eIF5A hypusination in tumor stromal lesions had TNM stage III and IV tumors (p = 0.012)." (PMID 38689086, 2024). "Multiple tumor suppressor genes like PHF23, EIF5A, KCTD11, MAP2K4 and ALOX15B, have been reported to promote tumorigenesis when lost, indicating that gene expression regulation, signal transduction, arachidonate lipoxygenase and other cellular pathways are altered with the loss of chromosome 17p." (PMID 36750552, 2023). "Finally, we used TIMER database determine the correlations between GALNT3, CYCS, EIF5A, and ITGB4 and six types of tumor-infiltrating immune cells." (PMID 35651789, 2022). "Lack of eIF5A or its inhibition of it led to a reduction in tumour spheroid growth revealing a function of eIF5A, contradictory to the previous study." (PMID 36511302, 2022). "Of these genes, EIF5A and ARNTL2 were significantly overexpressed in tumor cells (p < 0.05)." (PMID 34746138, 2021). "Moreover, in some subsets including CD8 TEM, SU increased the level of tumor immunity-related genes, including CD47, PCBP2, EIF5A, and PDIA3." (PMID 34824394, 2021). "However, a targeted shRNA library screen identified EIF5A, AMD1, SRM, and DHS as tumor suppressors in the Eμ-MYC model." (PMID 29799508, 2018). "Genetic knockdown of eIF5A inhibited PDAC cell growth in vitro and orthotopic tumor formation in vivo, potentially through pseudopodium-enriched atypical kinase 1 (PEAK1), which is essential to PDAC tumor growth, metastasis, and gemcitabine resistance." (PMID 28083147, 2016). "Therefore, eIF5A and DOHH have been proposed as targets for anti-tumor and anti-retroviral chemotherapy." (PMID 22438895, 2012). "Immunofluorescence analysis of allograft tumor tissues revealed that BPTES reduced the protein levels of CD80, CD204, hypusinated eIF5A, and HIF-1α, indicating that inhibition of HCC growth can be achieved by targeting eIF5A hypusination in TAMs via regulation of glutamine metabolism." (PMID 38689086, 2024).
tumor (continued). "However, to date, only few reports have documented the effect of EIF5A inhibition on in vivo tumor growth and it is not clear which translational targets mediate the EIF5A effect." (PMID 33303756, 2020). "On the other hand, in the protein expression profile of SSC-2, the neoplastic proliferation of tumor cells was related to the overexpression of PCNA, MPM2, KRAS, STAT3, EGFR, and bFGF and was supported by the overexpression of the protein translation factors eIF5A, DHS, and DOHH compared to SSC-1." (PMID 28789700, 2017). "Finally, eIF5A levels in tumor stromal lesions were greater than those in nontumor stromal lesions." (PMID 38689086, 2024). "Immunoreactivity related to eIF5A hypusination and CD204 expression in nontumor stromal lesions and tumor stromal lesions was scored from 0 to 2+ according to the intensity of staining." (PMID 38689086, 2024). "Immunohistochemical analysis revealed predominantly higher expression (immunoreactivity score of 2+) of eIF5A and CD204 in tumor stromal lesions than in nontumor stromal lesions; lower expression levels of these proteins were more common in noncancer stromal lesions (all p < 0.001)." (PMID 38689086, 2024). "Here we performed in silico analyses, evaluated the protein levels of EIF2S1, EIF5A and EIF6 in tumour samples and non-neoplastic tissue controls obtained from 145 patients, and correlated these results with clinical outcome data, including tumour site, stage, adjuvant radiotherapy and survival." (PMID 34830804, 2021).
infection (22 papers, 2008 to 2025). The state of being infected such as from the introduction of a foreign agent such as serum, vaccine, antigenic substance or organism. "For example, a transcriptomic study of a systemic symptomatic infection associated with runaway HR necrosis conferred by a soybean R gene in response to a virulent isolate of soybean mosaic virus identified eIF5A as a highly induced gene." (PMID 30450108, 2018). "Displaying a steep dose-effect curve, deferiprone produced infection-independent deficiency of hydroxylated hypusyl-eIF5A." (PMID 27191165, 2016). "Specifically, a pharmacologically or genetically induced defect of hypusine-containing eIF5A in culture both activates apoptosis in susceptible cells and inhibits infection by human or feline immunodeficiency virus." (PMID 24086341, 2013). "The results further support the observation that the RNA encoding the eIF-5A gene is present in the erythrocytic stages after infection with schizonts expressing the DHS -shRNA #176 (lane 4)." (PMID 22694849, 2012). "Phosphorylation enables EF-P activation in response to host defence during infection, which is similar to eukaryotic eIF5A, whose hypusination is dynamically regulated during stress." (PMID 41204333, 2025). "With respect to SPD, SPD-dependent modification of the eukaryotic translation initiation factor 5A protects against infection with H. pylori and C. rodentium by enhancing antimicrobial response and autophagy." (PMID 39102375, 2024). "We observed similar numbers of tdTomato+ SCs in the eIF5A-KO and WT controls, indicating that the infection efficiency and translation efficiency of tdTomato mRNA were similar in KO and WT cells." (PMID 39251577, 2024). "Additional exploration of mechanisms connecting hypusinated eIF5A to viral and cellular factors involved in infection will further illuminate how this molecule and polyamines support the replication of diverse viruses." (PMID 37071661, 2023). "A549 cells were infected with vesicular stomatitis virus (VSV) or influenza A virus (IAV) at a MOI of 5 and at different times after infection we analyzed the activation of eIF5A using Western blot analysis with anti-hypusine antibody." (PMID 35967877, 2022). "Mechanistic insight into the processes mediated by eIF5A and implicated in EBOV replication deserves to be further studied and will contribute to the development of therapeutic strategies to fight against infection." (PMID 34952646, 2021). "Ad-eIF5A-shRNA transduction provided the most effective means to deplete eIF5A, with nearly 100% infection of HeLa cells." (PMID 27180817, 2016). "By contrast, the eIF-5A sequences were clearly detected in the erythrocytic stage after infection with schizonts, which were transfected with the dhs-specific shRNA #176 vector (lane 1)." (PMID 22694849, 2012). "Significant upregulation of eIF5A was only observed in C6/36 cells after infection by intact Den-2 virus as detected by a quantitative real-time PCR." (PMID 20819232, 2010). "However, A549 cells were more sensitive to eIF5A-induced apoptosis with 16% and 19% of cells undergoing apoptosis forty-eight hours after infection with Ad-eIF5A1 or Ad-eIF5A1K50A, respectively." (PMID 23638878, 2013). "Blood samples, which were taken from the infected mice at day 5 post infection with either the expressed EIF-5A-shRNA or the DHS-shRNA were analyzed by RT-PCR and Western blot techniques, demonstrating the absence of either the hypusinated form of eIF-5A or DHS." (PMID 22694849, 2012). "As the proof of principle in our studies, inhibitors targeting polyamine pathway (DFMO, clofazimine, ribavirin) and eIF5A hypusination (GC7) can be used as antivirals to block latent and lytic replications as well as de novo infection of KSHV." (PMID 35486659, 2022).
infection (continued). "More specifically, levels of eIF5A, eIF5B, eIF1A, eIF4H proteins, and ribosomal proteins 40S and 60S were significantly decreased in PAMs after HP-PRRSV HN07-1-infection." (PMID 35498732, 2022). "A DHS-specific RT-PCR was performed to control formation of the 1248 bp cDNA fragment in the erythrocytic stages after infection of NMRI mice with transgenic schizonts harbouring the DHS-shRNA #176 and the eIF-5A #18 construct (lanes 1–2)." (PMID 22694849, 2012). "In two independent, different sets of experiments infection of mice was monitored after transfection of recombinant schizonts expressing either the P #176 DHS-shRNA, or the P #18 construct (eIF-5A-shRNA)." (PMID 22694849, 2012). "Western blot analysis of A549 cells expressing or not eIF5A at different times after infection with VSV using anti-VSV-G antibody revealed a clear reduction in the viral protein synthesis in absence of eIF5A1." (PMID 35967877, 2022). "In 3 independent western blot analyses (P<0.05), as shown in, compared with the H1N1pdm09 infection, the down- or up-regulated proteins of CAPZA1 (33KDa), OAT (49KDa), PCBP1 (37KDa), EIF5A (18KDa), PAFAH1B2 (26KDa) in H7N9 infection were consistent with the 2-D DIGE results." (PMID 27223893, 2016). "If there is indeed a direct interaction between eIF5A and VP30 mRNA, a highly speculative hypothesis is that it is sequestering eIF5A from the translation of other cellular proteins which, in turn, may facilitate infection." (PMID 27460797, 2016). "Ad-eIF5A1 and Ad-eIF5A1K50A infection of A549 cells did not deplete hypusine-eIF5A1 levels, indicating that the consequences of eIF5A1 and eIF5A1K50A over-expression are due to accumulation of non-modified eIF5A1 and not to depletion of hypusine-eIF5A levels." (PMID 23638878, 2013). "Another important observation is that apoptosis induced by Ad-eIF5A1 or Ad-eIF5A1K50A infection was not correlated to a reduction in hypusine-eIF5A levels, suggesting that the apoptotic response is not a result of depletion of the hypusinated form of the protein." (PMID 23638878, 2013).
neurodevelopmental disorder (7 papers, 2021 to 2024). A behavioral and cognitive disorder with onset during the developmental period that involves impaired or aberrant development of intellectual, motor, or social functions. "Recently, patient-derived variants of DHS and eIF5A have been linked to rare neurodevelopmental disorders." (PMID 36973244, 2023). "The fact that these variants lead to neurodevelopmental disorders suggests that, among all other organs and tissues, brain is most sensitive to a deficiency in biologically active eIF5A." (PMID 34273022, 2022). "Future studies will be directed toward elucidation of molecular mechanisms underlying these neurodevelopmental disorders stemming from a reduction in bioactive, hypusinated eIF5A and the identification of downstream effectors of eIF5A." (PMID 34688659, 2021). "More recently, germ line, de novo, heterozygous EIF5A variants were also reported to be associated with a neurodevelopmental disorder." (PMID 34688659, 2021). "Variants in EIF5A or DHPS were recently identified as the genetic basis underlying certain rare neurodevelopmental disorders in humans." (PMID 34688659, 2021). "Recent genetic studies have provided evidence that certain variants in the EIF5A or DHPS gene are associated with rare neurodevelopmental disorders in humans." (PMID 34688659, 2021). "These cognitively impaired CKO mice hold potential utility in the future development of chemical or biological therapeutics for human neurodevelopmental disorders caused by variants of EIF5A, or DHPS." (PMID 34688659, 2021). "These mice display impairment in growth, lifespan and cognitive functions, reflective of phenotypes of human patients, and may serve as useful tools in the development of chemical or biological therapeutics against neurodevelopmental disorders caused by variants of EIF5A, DHPS, or DOHH." (PMID 34273022, 2022). "From whole trio exome sequencing, variants in EIF5A, DHPS, and DOHH genes were identified as the basis of certain rare neurodevelopmental disorders in humans." (PMID 34273022, 2022). "Biallelic variants in DOHH are also associated with a neurodevelopmental disorder and fibroblasts derived from these individuals have decreased DOHH enzyme activity, the accumulation of the intermediate deoxyhypusine eIF5A, and the consequent reduction of eIF5AHyp." (PMID 39125743, 2024).
degenerative disease (1 paper, 2024). "The spermidine-eIF5A axis might therefore represent a pharmacological target that can be mobilized to counteract degenerative disease via activating endogenous adult stem cells." (PMID 39251577, 2024).
genetic diseases (1 paper, 2021). "Moreover, the recent use of genomic and transcriptomic association along with metadata studies also revealed the implication of eIF5A in genetic diseases." (PMID 34952646, 2021).
heart disease (1 paper, 2023). "Our findings are relevant to human heart disease, as increased hypusinated eIF5A levels were observed in heart samples of ischemic heart failure patients compared to healthy subjects." (PMID 36826549, 2023). "eIF5A is not transcriptionally upregulated in TGFβ-activated human CFs from heart disease patients or end-stage failing human hearts." (PMID 36826549, 2023).
EIF5A also shares sentences with these, for which no sentence is quoted: Intellectual disability (5 papers); Glucose intolerance (3); Micrognathia (3); cervical cancer (2); colorectal adenoma (2); multiple myeloma (2); Obesity (2); acute kidney injury (1); acute lymphoblastic leukaemia (1); aortic aneurysm (1); B-Cell lymphoma (1); bladder cancer (1); brain tumors (1); cervical and (1); cervical tumors (1); chronic myelogenous leukemia (1); colitis (1); congenital microcephaly (1); diabetic retinopathy (1); endometrial cancer (1); esophageal cancer (1); fibrosis (1); gastric cancer (1); glaucoma (1); Hyperglycemia (1); infectious disease (1); intestinal type adenocarcinoma (1); ischemic disease (1); Kabuki syndrome (1); leiomyoma (1).
A further 15 diseases each share a sentence with EIF5A in 1 paper.